CLDN3 (claudin 3)
Diseases named in the same sentence as CLDN3 in open-access papers (continued):
Sharing a sentence is not in itself a finding about the gene and the disease.
colorectal cancer (15 papers, 2013 to 2025). A primary or metastatic malignant neoplasm that affects the colon or rectum. "Claudin-3 (CLDN3) is associated with colorectal cancer progression, while Cadherin-17 (CDH17) correlates with unfavorable prognosis in various cancers." (PMID 40452847, 2025). "In colorectal cancer cells, the expression level of CLDN3 is abnormally increased, and its overexpression is associated with the deterioration of colorectal cancer." (PMID 38493179, 2024). "We further analyzed the expression of EpCAM and CLDN3 in several cancers, including ovarian, gastric, and colorectal cancers." (PMID 40057807, 2025). "Contradictory findings from these two studies on the involvement of CLDN3 in colorectal cancer indicate that we still know very little about the role of CLDN3 in colorectal cancer." (PMID 36620607, 2022). "Specific inactivation of tyrosine kinase receptors, mediated by phospholipase C (PLC), as well as a signal transducer and activator of transcription 3 (STAT3), leads to a decrease in claudin-3 levels in colorectal cancer." (PMID 34638619, 2021). "In colorectal cancer cells, claudin 3 overexpression promoted the malignant potential of cells, probably via epidermal growth factor-activated ERK1/2 and PI3K-Akt pathways." (PMID 29482498, 2018). "This is in line with other studies, which show an upregulation of claudin-3 and -4 in colorectal cancers compared to their expression in normal mucosa." (PMID 28193196, 2017). "Conversely, upregulation of CLDN3 play fundamental role to promote the development of colorectal cancer, which is potentially regulated by the EGF-activated downstream pathway, ERK1/2 and PI3K-Akt signaling pathways." (PMID 28160565, 2017). "In conclusion, our results show a novel role for claudin-3 overexpression in promoting the malignant potential of colorectal cancer cells, which is potentially regulated by the EGF-activated ERK1/2 and PI3K-Akt pathways." (PMID 24069372, 2013). "Our findings revealed that the mRNA expression levels of CLDN1, CLDN2, CLDN12, and CLDN14 were upregulated in colorectal cancer tissues relative to normal tissues in the Oncomine database, whereas CLDN3, CLDN5, CLDN7, CLDN8, CLDN11, CLDN15, and CLDN23 were downregulated, as previously reported." (PMID 35281827, 2022). "The overexpression of c-kit or administration of its ligand stem cell factor increased expression of the tight junction protein claudin-3 in colorectal cancer cells in vitro, and decreased claudin-3 expression was observed in the colon epithelium of mice lacking functional c-kit." (PMID 29922293, 2018). "In conclusion, the present study clearly revealed that activation of SCF/c-kit/JNK/AP-1 signaling axis could obviously up-regulate claudin-3 expression in the colonic epithelium and colorectal carcinoma." (PMID 28383479, 2017). "We further demonstrated that the increased expression of claudin-1 and claudin-3 differentially affected colorectal cancer cells; in HT-29 cells, the forced expression of claudin-1 decreased cell migration, whereas the forced expression of claudin-3 increased the malignant potential." (PMID 24069372, 2013). "Studies have revealed that SCF/c-kit signaling exclusively enhances CLDN3 expression in colorectal cancer, mainly by activating the JNK pathway, and that the SCF/c-kit-JNK-AP-1 signaling axis is crucial for controlling CLDN3 expression." (PMID 36620607, 2022). "However, when comparing colorectal cancer tissues from the GEPIA database to normal colonic mucosa, the mRNA level expression of CLDN3, CLDN7, and CLDN23 was shown to be significantly higher in these tumor tissues." (PMID 35281827, 2022). "Most importantly, our results reveal that claudin-3 plays a role as tumor promoter when its expression is imbalanced and implicate the ERK1/2 and PI3K-Akt signaling pathways as modulators of claudin-3 upregulation-related tumor progression in colorectal cancer cells." (PMID 24069372, 2013).
lung carcinoma (12 papers, 2011 to 2025). "CLDN3 and 4 were also described as potent regulators of chemoresistance in ovarian and lung cancer, and targeting CLDN3 transcription with small molecules effectively suppressed cancer stemness and reversed their chemoresistance." (PMID 40943068, 2025). "Tested lung cancer cell lines expressed not only Cldn1, but also Cldn3, Cldn4, and Cldn7 (PC‐9 cells) or Cldn3 (SK‐Mes‐1 cells)." (PMID 31825142, 2020). "Here, claudin-3 overexpressing lung cancer cells were insensitive to cisplatin treatment compared to control cells." (PMID 31861759, 2019). "Such CPE mediated treatment could also be one option in treatment of claudin 3 or 4 positive lung cancer." (PMID 21619599, 2011). "Of them, 6 miRNAs (miR-149, miR-205, miR-375, miR-378, miR-422a and miR-708) and 9 target genes (CEACAM6, CGN, CLDN3, ABCC3, MLPH, ACSL5, TMEM45B, MUC1) were validated by quantitative PCR in an independent cohort of 41 lung cancer patients." (PMID 24625834, 2014). "In addition to claudin 3 and 4 which may have therapeutic implications for tumor treatment in the future, claudin 18 might also be a new target for antibody mediated therapy in lung cancer." (PMID 21619599, 2011). "The expression of claudin-3 in ovarian, prostate, breast, pancreatic and lung cancers could promote tumor invasion and development, but the effect of claudin-3 on melanoma progression and metastasis has not been addressed so far." (PMID 36261482, 2022).
ovarian tumor (12 papers, 2005 to 2021). "Interestingly, we also detected a marked decrease in the association with claudin-3, a tight junction protein and a driver of ovarian tumor growth and metastasis." (PMID 25356755, 2014). "The reported overexpression of claudin-3, -4, and -7 in ovarian tumors suggests, on the contrary, a cancer-promoting role that is largely unexplained." (PMID 32850397, 2020). "It has also been suggested that claudin-3 drives ovarian tumor progression and metastasis by controlling cell-cell contacts and Wnt signaling." (PMID 25356755, 2014). "Another novel approach of targeting claudin-3 and -4 expressing ovarian tumor cells is through gene therapy." (PMID 23685873, 2013). "CLDN3 siRNA showed potent suppression of both tumor growth and metastasis in mouse and human ovarian tumor xenografts." (PMID 24009024, 2013). "CLDN3 small interfering RNA (siRNA) inhibits tumor growth and metastasis in mouse and human ovarian tumor xenografts, further supporting the cancer-promoting role of claudin-3." (PMID 24009024, 2013). "Chemotherapy-resistant ovarian cancer was found to express the claudin-3 and -4 genes at significantly higher levels when compared with chemotherapy-naïve ovarian tumors." (PMID 23685873, 2013). "Our previous studies suggest that chemotherapy-resistant ovarian tumors express extremely high levels of claudin-3 and -4 and that these tumors are highly sensitive to CPE in vitro." (PMID 20598131, 2010). "In ovarian tumours, the same group suggested that CLDN3 and CLDN4 are required for signalling through survival or proliferative pathways." (PMID 15743508, 2005). "Contrary to the findings in ovarian tumours reported by Rangel and coworkers that CLDN3 and CLDN4 exhibited cytoplasmic staining and that over-expression of these proteins were associated with malignancy, in our study in breast we did not observe clear positivity of CLDNs in cytoplasm." (PMID 15743508, 2005). "Conceivably, CD151 may regulate ovarian tumor growth and dissemination, at least in part, by sequestering the function of tumor-promoting molecules such as CD9 and claudin-3 within the TEMM in ovarian tumor cells." (PMID 25356755, 2014).
hepatocellular carcinoma (10 papers, 2013 to 2025). A malignant tumor that arises from hepatocytes. "Conversely, CLDN3 downregulation, frequently reported in human liver cancer, was associated with a worse prognosis of patients with hepatocellular carcinoma." (PMID 32664456, 2020). "CLDN3 expression inhibits cell motility and invasiveness of hepatocellular carcinoma cells, suggesting a role as metastasis suppressor gene in this tumor type." (PMID 36614243, 2023). "For CLDN3 it has been observed that it methylation occurs in esophageal and hepatocellular carcinoma." (PMID 26198249, 2015). "In contrast, the ectopic expression of CLDN3 in hepatocellular carcinoma cells could inhibit tumorigenesis and cancerous cells migration and invasion." (PMID 28160565, 2017).
pancreatic cancer (10 papers, 2006 to 2025). "This was further confirmed by IHC for Cldn3/4, showing the specific membranous expression within the pancreatic cancer PDX tissue." (PMID 34503203, 2021). "For sensitivity testing of Cldn3/4 expressing pancreatic cancer cell lines toward recombinant CPE (recCPE) protein, increasing recCPE concentrations from 0 to 250 ng mL−1 were applied for 72 h and cytotoxicity was measured." (PMID 34503203, 2021). "The binding ability of CPE to claudins, especially claudin-3 and claudin-4, has raised a great opportunity to target cancers with dysregulated claudin-3 and -4 cancers, especially breast, ovarian, and pancreatic cancers." (PMID 31861759, 2019). "One member of the claudin family, claudin-3, has been shown to be overexpressed in breast, ovarian, and pancreatic cancer." (PMID 21255442, 2011). "CLDN3,4,7 were expressed in tumors of the pancreas, bladder, thyroid, fallopian tubes, ovary, stomach, colon, breast, uterus, and prostate." (PMID 16836752, 2006). "In particular, claudin-3 and claudin-4 are frequently overexpressed in pancreatic cancer." (PMID 29258264, 2017). "Additionally, claudin-3 and -4 have also been shown to be overexpressed in cancers including gastric, ovarian, and pancreatic cancers." (PMID 24204396, 2013). "For example, CLDN3, and CLDN4 have been found frequently up-regulated in ovarian, breast, prostate and pancreatic tumors." (PMID 16836752, 2006). "This leads to decreased tumor viability and increased tumor growth inhibition in the human pancreatic cancer CDX models with comparable degree, independent of the Cldn3/4 expression level." (PMID 34503203, 2021).
lung adenocarcinoma (9 papers, 2014 to 2025). A carcinoma that arises from the lung and is characterized by the presence of malignant glandular epithelial cells. "CLDN3 expression was significantly increased in lung adenocarcinoma tissues and it was associated with cancer progression and poor survival." (PMID 33597819, 2021). "Loss of claudin 3 expression increases the metastatic ability of esophageal cancer, whereas claudin 3 is upregulated in lung adenocarcinoma." (PMID 29285217, 2017). "Overall, we have indicated a consistent and significant increase in CLDN3 expression in lung adenocarcinoma and a causal association between CLDN3 overexpression and prognosis of ADC patients." (PMID 28160565, 2017). "In lung adenocarcinoma, it enhances metastasis by upregulating CLDN3 through the Wnt/β-catenin pathway." (PMID 40389954, 2025). "In conclusion, our results demonstrate a novel role of CLDN3 overexpression in promoting the malignant potential of lung adenocarcinoma." (PMID 28160565, 2017). "The results above suggest that CLDN3 acted as an oncogene in human lung adenocarcinoma, and CLDN3 overexpression significantly increased the tumorigenicity and development of both cell types under study." (PMID 28160565, 2017). "The survival curve analysis showed that high expression of CLDN3 is correlated with poorer rates of survival in lung adenocarcinoma patients." (PMID 29285217, 2017). "Similar as CLDN3 overexpression in colonic and ovarian cancers, CLDN3 expression is increased in most of lung adenocarcinoma." (PMID 28160565, 2017). "In the GSE10072 array, we also observed that expression levels of AGR2 and CLDN3 are significantly upregulated in lung adenocarcinoma when compared to normal lung tissue." (PMID 29285217, 2017). "However, the underlying mechanisms that regulate the function and expression of CLDN3, particularly in lung adenocarcinoma, are poorly understood." (PMID 28160565, 2017). "Also, in lung adenocarcinoma CLDN3 overexpression resulted in promoting the malignant potential." (PMID 32664456, 2020). "Our study showed that claudin 3 may have oncogenic effects in lung adenocarcinoma." (PMID 29285217, 2017). "In this process, CLDN3 overexpression is modulated by the EGF pathway and has been observed to promote the malignant potential of lung adenocarcinoma." (PMID 39720074, 2024). "Lung adenocarcinomas developing after AD-CRE and TAT-CRE application expressed claudin-3 similarly." (PMID 40360735, 2025). "The analysis of the effects from each gene expression on survival outcome indicated that 6 genes (AGR2, SPDEF, CDKN2A, CLDN3, SFN, and PHLDA2) play oncogenic roles, and 7 genes (PDK4, FMO2, CPED1, GNG11, IL33, BTNL9, and FABP4) act as tumor suppressors in lung adenocarcinoma." (PMID 29285217, 2017). "In addition, factors previously identified to be specific markers of lung adenocarcinoma were upregulated, including PROM2, CLDN3, and TJP3, as were genes proposed to have potential diagnostic or prognostic value in human cancers, including MMP9, AGR2, SULF1, NHSL1, LGR5, MUC1, and PIK3C2G." (PMID 31434729, 2019).
endometrial cancer (8 papers, 2005 to 2025). Primary or metastatic malignant neoplasm involving the endometrium (mucous membrane that lines the endometrial cavity). "Indeed, overexpression of CLDN-3 and -4 is associated with progression of disease and poor clinical outcome in endometrial cancer patients 10-12." (PMID 36484008, 2022). "In the current study, we have shown overexpression of claudin-3 and -4 mRNA (by RT-PCR) and protein (by immunoblotting) in a panel of 9 human endometrial cancer cell lines." (PMID 36484008, 2022). "The expression of CLDN-3 and -4 proteins in a panel of nine endometrial cancer cell lines was determined by immunoblot analysis." (PMID 36484008, 2022). "To investigate the mechanism of CLDN-3 and -4 protein overexpression, we subjected RNA isolated from the same panel of endometrial cancer cell lines to RT-PCR analysis using primers targeted to the CLDN-3 and -4 genes." (PMID 36484008, 2022). "Using immunoblot analysis, we demonstrated overexpression of the CLDN-3 and -4 integral membrane proteins in 4 of 9 and 5 of 9 endometrial cancer cell lines, respectively." (PMID 36484008, 2022). "During endometriosis, decreased expression levels of CLDN-3, -4, and -7 have been observed, and in endometrial cancer, increased expression levels of CLDN-3 and -4 have been reported." (PMID 31330820, 2019). "A downregulation of expression of OCLN and CLDN-3, -4, and -7 has been observed in endometriosis, and an upregulation of expression of CLDN-3 and -4 has been reported in endometrial cancer." (PMID 36291839, 2022). "Whereas the THESCs cells expressed barely detectable levels of CLDN-3 and -4 proteins, we observed dramatic overexpression of CLDN-3 in AN3-CA, EFE-184, MFE-280 and MFE-319 endometrial cancer cell lines relative to THESCs." (PMID 36484008, 2022). "Treatment significantly prolonged the survival of tumor-bearing mice, suggesting that CLDN3 and CLDN4 may represent promising therapeutic targets for the management of aggressive, treatment-resistant type II endometrial cancers." (PMID 40687428, 2025). "Claudins-3 (CLDN3 – claudin 3) and -4 (CLDN4 – claudin 4) were elevated in endometrial cancer." (PMID 39176196, 2024). "In addition, although the overall levels of CLDN-4 protein were lower compared with those of CLDN-3, we also observed overexpression of CLDN-4 in the EFE-184, MES-SA, MFE-296, MFE-319 and RL95-2 endometrial cancer cell lines relative to THESCs." (PMID 36484008, 2022). "In addition to the expected frequent overexpression of the much studied CLDN-3, CLDN-4 and OCLN genes, we also observed overexpression of an additional 21 TJ genes in at least one of the endometrial cancer cell lines." (PMID 36484008, 2022). "Following knockdown of LSR in endometrial cancer Sawano cells, CLDN-1 expression increased, while there was no significant change in the expression levels of CLDN-3, -4, -7, and OCLN." (PMID 31330820, 2019).
breast tumor (7 papers, 2005 to 2018). "We tested this profile (TN and low expression of at least two of four epithelial cell-cell adhesion markers; claudin 3, claudin 4, claudin 7 and E-cadherin) in a large cohort of breast tumors with long-term follow up." (PMID 28045912, 2017). "These distinct tumors were found in both human and murine breast tumor data sets and were characterized by the low gene expression of tight junction proteins claudin 3, 4 and 7 and E-cadherin, a calcium-dependent cell-cell adhesion glycoprotein." (PMID 20813035, 2010). "In addition, these tumors had low expression of claudin 3 and claudin 4, possibly implying the claudin-low subtype of breast tumor." (PMID 25938540, 2015). "Although the similar CLDN3 and CLDN4 TJ proteins are highly expressed in breast neoplasia, we hypothesize that mechanisms other than alteration in TJs are involved in the loss of CLDN1 expression in breast tumours." (PMID 15743508, 2005). "Many tumor types such as colon and breast tumor, are characterized by a reinforced expression of the CPE receptors claudin-3 -4 or -723,24,43–45." (PMID 30297847, 2018). "On the other hand, claudin-3, a tight junction protein depleted in CD44+/CD24- CSC enriched basal/mesenchymal breast tumors, was among the most down regulated genes in SK-β1-C1." (PMID 23991019, 2013). "This cluster had low expression of the claudin genes CLDN3, CLDN4, and CLDN7, raising the possibility that tumors in this cluster were members of the claudin-low subtype, a group of breast tumors known for their invasive, mesenchymal-like behavior." (PMID 23667446, 2013).
mastitis (6 papers, 2019 to 2025). Inflammation of breast tissue during lactation or postpartum due to an obstructed duct or infection. "We further investigated the effect of SA on the blood-milk barrier by assessing the expression of the tight junction (TJ) protein ZO-1, Occludin, and Claudin-3, which are disrupted during mastitis." (PMID 37069691, 2023). "Our previous research results show that repairing the blood-milk barrier during the inflammatory response is beneficial to the relief of mastitis, such as promoting the expression of claudin-3 protein, which is beneficial to the relief of mastitis." (PMID 34383710, 2021). "Lipopolysaccharide-induced mastitis disrupts the blood-milk barrier by altering claudin composition (e.g. claudin-3 phosphorylation and claudin-4/7 recruitment) in mammary alveolar tight junctions, facilitating the influx of neutrophils and red blood cells into mammary acini." (PMID 41343264, 2025).
ulcerative colitis (6 papers, 2016 to 2024). An inflammatory bowel disease involving the mucosal surface of the large intestine and rectum. "In colonic biopsies from patients with ulcerative colitis, reduced or redistributed of claudin-3 and -4 association with increased permeability has been reported." (PMID 27551722, 2016). "Several studies have reported increased expression of claudin-1 and -2 and a reduction in claudin-3 and -4 expression in ulcerative colitis." (PMID 39334888, 2024). "Knockout studies of Claudin genes result in loss of tight junction barrier function, with the dysregulation of Claudin-3 gene reported in IBD (both Crohn’s disease and ulcerative colitis) and celiac disease." (PMID 38542520, 2024). "It demonstrated that POG effectively alleviated the decrease of Occludin, Claudin-3, and ZO-1 protein levels in the DSS-induced mice ulcerative colitis model." (PMID 35662727, 2022). "In conclusion, our immunofluorescence and immunoblotting detection of claudins consistently demonstrates the suppression of claudin-1 and -4, the increase in claudin-2, and no change in the claudin-3 isoform in the present model of ulcerative colitis, all of which are reversed by nobiletin." (PMID 39334888, 2024).